PDGFRB (platelet derived growth factor receptor beta)
Diseases named in the same sentence as PDGFRB in open-access papers (continued):
Sharing a sentence is not in itself a finding about the gene and the disease.
tumor (continued). "The affibody-IR700 conjugate displayed a high affinity for PDGFRb and was shown to induce cell death in PDGFRb+ pericytes but not in PDGFRb- tumor cells." (PMID 36839652, 2023). "Inhibition of PDGFRB signaling could result in the down-regulation of IL6 and TGFB1/2 in CAFs and suppressed expression of immune checkpoints in tumor cells, leading to immune cytotoxicity." (PMID 37658364, 2023). "Based on our speculation, we propose that α-SMA+, PDGFRB+, and IGFBP7+ CAFs play a role in tumor immunotherapy response." (PMID 37568781, 2023). "Most of these cells were tumor epithelial cells, characterized by high expression of keratin 19 (KRT19) and low expression of PTPRC (CD45), PECAM1 (CD31), and PDGFRB, which are markers for immune/hematopoietic cells, endothelial cells, and stromal cells, respectively." (PMID 37966117, 2023). "Additionally, sorafenib can target the platelet-derived growth factor receptor beta (PDGFR-β), the vascular endothelial growth factor receptor (VEGFR) 2, and the hepatocyte factor receptor (c-Met), among other proteins, to inhibit tumor angiogenesis." (PMID 37296859, 2023). "In oral tumour cells, secreted LOXL2 oxidises lysine residues in platelet-derived growth factor receptor beta (PDGFRβ) on stromal fibroblasts, enhancing platelet-derived growth factor (PDGF-AB) signalling and promoting stromal fibroblast proliferation via ERK activation." (PMID 37762708, 2023). "Consistent with tumor suppression, pharmacological inhibition of TGF‐βR1 abrogated Bmal1‐deletion–triggered tumor fibrosis that showed reduced positive structures of FAP, α‐SMA, DESMIN, PDGFRα, and PDGFRβ." (PMID 37330661, 2023). "Moreover, PECAM1+ cells (ECs) in cluster 8 ECS (COL1A1, COL1A2, COL3A1, PDGFRB, and ACTA2) showed an endothelial-mesenchymal transformation phenotype, which contributed to tumor progression." (PMID 37533434, 2023). "They used fresh-frozen tumor samples and tumor-derived cell lines and an increase in PDGFRβ phosphorylation was found in fresh frozen tumour samples, but it was not statistically significant." (PMID 36091939, 2022). "As tumor fibrosis is closely related to vessel normalization, we evaluated Pan02 tumor vasculature through immunofluorescence analysis of CD31 as an endothelial cell marker and NG2 or PDGFRβ as a pericyte marker." (PMID 36272973, 2022). "Patients with PDGFRβ expression on tumor cells (n = 11) had a significantly lower five-year EFS compared to patients lacking (n = 87) membrane-bound PDGFRβ." (PMID 36045346, 2022). "lncHOTAIR regulates tumor cell proliferation by binding to Y-Box Protein-1 and promoting its nuclear translocation, which stimulates Y-Box Protein-1 downstream targets PCK2 and PDGFRβ." (PMID 36014574, 2022). "In addition, the ACTA2, ASPN, PDGFRB, PDPN, COL12A1, EMILIN1, and CDH11 genes were upregulated in CAFs of several tumor types." (PMID 36263012, 2022). "CRC EVs had a variety of different effects on other CAF markers (e.g., PDGFRβ or periostin), suggesting that they may play a role in the formation of different (non‐myofibroblastic) CAF subtypes in tumour stroma." (PMID 35595718, 2022). "Also, the angiogenesis-related molecules including PDGFB, VEGF, VEGFA, and PDGFRB were significantly downregulated by MTE, especially by high-dose MTE in the HCC-PDX tumor." (PMID 35847002, 2022). "First, we categorized clustered data into tumor and stromal populations using a panel of markers for each (epithelial: AQP1, AQP2, EPCAM; endothelial: PLVAP, CD31, CD34; fibroblast: PDGFRα, PDGFRβ; immune: CD45; tumor cell: CXCR4, VIM, KRT18, PAX8, PAX2, CA9, CD10)." (PMID 34884982, 2021). "Even though tumor cell PDGFRB expression was higher in the unfavorable tumor architecture group, the negative effect of high tumor cell PDGFRB on survival was seen in both groups." (PMID 33955203, 2021).
tumor (continued). "A subpopulation of these cellular elements also co-labeled with PDGFRβ, a key regulator of mesenchymal cell activity in the tumor microenvironment, while most of them were negative for α-smooth muscle actin (α-SMA) expression (data not shown)." (PMID 34094919, 2021). "However, carbotinib has fairly multiple anti-tumor targets, including VEGFR2, MET, PDGFRβ, and so on." (PMID 33892656, 2021). "For instance, the αSMA, PDPN and PDGFRβ+ populations showed a decrease over time in the CAF+ population, with linear fitting of the data indicating similar temporal dynamics of all three markers in both 4T1 and 4T07 tumours." (PMID 34016130, 2021). "There was no clear difference in relative tumor PDGFRB area and histology due to the large variation and limited sample size." (PMID 33955203, 2021). "In contrast to FAP+ cells and THY1+ cells, the overall percentages of NT5E+ cells, TNC+ cells, and PDGFRβ+ cells were not altered in the tumor microenvironment compared to benign prostate stroma." (PMID 33600062, 2021). "While the overall expression of NT5E, TNC, and PDGFRβ did not change in the tumor microenvironment, ASPN expression was altered in these cells." (PMID 33600062, 2021). "In contrast, IGF-1 and PDGFR may be relevant to COM, and patients with tumours positive for both PDGFRα and PDGFRβ have significantly shorter overall survival." (PMID 34822659, 2021). "We found that GFPpos tumor cells expressed nearly no detectable Pdgfrβ and drastically reduced p-Pkcα, p-Fra1, and Vim, when compared with GFPneg tumor cells." (PMID 33478572, 2021). "We found that Pdgfrβ WT p18−/−;Brca1MGKO tumor cells generated palpable tumors in 10–14 days whereas Pdgfrβ KO cells did not generate palpable tumors in the same time period." (PMID 33478572, 2021). "In a follow up experiment, we co-stained frozen tumor sections for GARP and PDGFRβ." (PMID 34386010, 2021). "PDGFRA and PDGFRB displayed high expression in 59% and 22% of samples, respectively, whereas high SFK phosphorylation was seen in approximately half of all tumours." (PMID 33478100, 2021). "Inhibition of PDGFRβ-PKCα signaling specifically targets oncogene-transformed MECs that have undergone EMT and induces mesenchymal-to-epithelial transition (MET), suppressing tumor initiation and progression." (PMID 33478572, 2021). "Compared to normal tissues, elevated levels of PDGFRβ and THBS4 were found in tumor tissues, which confirms our hypothesis that these two proteins are significantly associated with tumor development in CRC." (PMID 32899998, 2020). "Interestingly, it has been shown that PDGFRβ-positive progenitor cells from the bone marrow are able to differentiate into α-SMA- and NG2-positive pericytes during tumor angiogenesis." (PMID 31938055, 2020). "Additionally, these compounds presented potent inhibition against the tumor growth-related tyrosine multiple kinase targets FGFR3, IGF1R, PDGFRb, and TRKB at a concentration of <10.4 μM, except for 151, which showed weak activity, with IC50 > 25 μM." (PMID 32570903, 2020). "In our previous report, we used a nuclease-resistant internalizing RNA aptamer, named Gint4.T, to bind and inhibit the platelet-derived growth factor β receptor (PDGFRβ), and then designed an AsiC (Gint4.T-STAT3) for the delivery of a STAT3 siRNA to GBM cells, inhibiting tumour cell growth." (PMID 32486489, 2020). "To determine the specific role of PDGFRβ in the tumor microenvironment, we have studied four tumor cell lines, with no or low PDGFRβ expression." (PMID 31938055, 2020). "We should emphasize while anti-VEGF had no impact on E0771 cancer cell proliferation in vitro, anti-PDGFRβ modestly inhibited tumor cell proliferation." (PMID 32709869, 2020). "Upregulation of PD‐L1, CD90, PDGFRβ, CD248 and Rgs5 which inhibit CD4+ and CD8+ cytotoxic T‐cell activity was reported in pericytes derived from within tumour microenvironments, which facilitates immunosuppression and eventual immune evasion of tumour cells." (PMID 32588948, 2020).
tumor (continued). "Until now it has not been possible to assess the specific role of PDGFRβ signaling in tumor progression and angiogenesis due to lack of appropriate animal models and molecular tools." (PMID 31938055, 2020). "In addition, we have also detected single pericyte‐like cells expressing the specific markers PDGFRβ and CD13, scattered among the tumor cells, especially in less cell‐dense areas, probably in the proximity of necrotic zones." (PMID 32534480, 2020). "Compounds 460–462 showed strong cytotoxicity against six HTCLs (HCT-116, HepG2, BGC-823, NCI-H1650, A2780, and MCF7) (IC50 = 1.3–12.5 μM) and exhibited selective significant inhibitory activity towards the human tumor-related protein kinases of FGFR3, IGF1R, PDGFRb, and TrKB (IC50 = 2.6–21.4 μM)." (PMID 32570903, 2020). "By reconstructing the tumor microenvironment using ER+BCCs, TAFs, and the immune cells from the same primary tumors, we demonstrate that the effectiveness of endocrine therapy (Tam) can be significantly augmented in the presence of IL1R1 and PDGFRβ blockers." (PMID 31419632, 2019). "They exhibited potent antitumor activity against a panel of tumor cell lines, including HCT-116 and HepG2, with IC50 values < 10 μg/mL, in addition to inhibitory activity against tumor growth-related tyrosine kinases, including FGFR3, IGF1R, PDGFRb, and TRKB." (PMID 31174259, 2019). "Furthermore, we identified that the addition of a PDGFRβ inhibitor enhances the efficacy of combined MEK1/2 and JAK2 inhibition in vitro and significantly hampered TNBC syngeneic tumor growth in vivo through intratumoral CD8+ T cells infiltration." (PMID 30777101, 2019). "But the keratin-positive epithelial cells were mainly localized in the tumor islands which were PDGFRβ-negative." (PMID 31690270, 2019). "For instance, CD44v isoform, an alternative splicing variant of CD44 containing v8–v10 exons, was convinced to drive tumor progression and metastasis by promoting BRCA stemness via activating the PDGFRβ/Stat3 cascade and PFKFB4-mediated glucose metabolism despite tumor-suppressing genetic origin." (PMID 30984247, 2019). "Unexpectedly, the addition of PDGFRβ inhibitor Nilotinib did not provide any additional suppression of tumor growth either alone or when combined with MEK1/2-JAK2 inhibitors in double or triple combination therapy." (PMID 30777101, 2019). "Tumour cells showed high expression of PDGFRα in 76 (56%) and PDGF-CC in 29 (22%) of synchronous lymph node metastasis, whereas stromal cells showed high expression of PDGFRα in 68 (50%) and PDGFRβ in 46 (34%)." (PMID 29380207, 2018). "In the present study we employed tumor models where PDGFRβ is expressed in the stroma but not by the tumor cells, i.e. KAT-4, CT-26 and B16BB tumors." (PMID 28231806, 2017). "Similarly to the other tumours generated in this study, these allograft tumours stained positively for PMEL, CATHEPSIN K, PDGFRβ, SMA and VIMENTIN, expressed PMEL by western blotting, and exhibited a similar frequency of PMEL expressing cells." (PMID 29133867, 2017). "As expected, α6-integrin is expressed on tumour endothelial cells, shown by co-expression of α6-integrin and the endothelial cell marker CD31, suggesting that the deletion of α6-integrin in vivo was restricted to PDGFRβ-positive pericytes." (PMID 28289267, 2017). "The conjugate of the ZPDGFRβ affibody and IR700 dye, i.e. ZIR700, bound to PDGFRβ+ pericytes but not to PDGFRβ− LS174T tumor cells." (PMID 29182023, 2017). "The tumor cells from lung biopsy in this case showed focal positive immunostaining for CD117 (c-kit) and vascular endothelial growth factor receptor-2 (VEGFR-2) and weakly positive for platelet-derived growth factor receptor beta (PDGFR-beta)." (PMID 27630780, 2016).
tumor (continued). "Surprisingly, co-localization of PDGFRα and PDGFRβ in T241 tumours by their specific antibodies showed that TAMs lacked PDGFR expression, suggesting an indirect role of PDGF-BB in the recruitment of TAMs." (PMID 27150562, 2016). "Subsequent analyses of OSCC specimens demonstrated that PDGFRβ was abundantly expressed in stromal fibroblasts, while it was absent in tumor cells, with greater specificity compared to other markers such as αSMA or podoplanin." (PMID 27128408, 2016). "Conversely, numerous fibroblasts expressing high levels of PDGFRβ were found in stroma surrounding tumor islands in all OSCC specimens (12/12), while no PDGFRβ expression was detected on tumor cells." (PMID 27128408, 2016). "Similar analyses performed on ten additional TCGA cancer datasets revealed that other tumor types shared CAF markers with OSCC, including PDGFRβ, which was found to significantly correlate with the reference collagen expression in ten of the 11 cancer types tested." (PMID 27128408, 2016). "Although the expression of six endothelial differentiation marker genes (PECAM1, vWF, FLT1, FLT4, KDR, CDH5) was significantly lower in normal and tumor ADSC, there was significantly greater expression of PDGFRB in ADSC when compared to BEC and NORMA1 MEC cells." (PMID 26968831, 2016). "In contrast, sar@LIP induced the up-regulation of a broad spectrum of genes related to the positive induction of cell proliferation (CCND1, E2F3, PDGFRB and TEGT, a described BAX inhibitor), which corresponds to the tumor growth enhancement observed in vivo after sar@LIP administration." (PMID 27646588, 2016). "On the other hand, the expression of CD166, CD133, CD44, A2B5, CD56, NGFR and DCX seemed to be higher in UA cells, but also not statistically significant, while the expression of CD9, Nestin, GFAP, CD24, PDGFRb, PDGFRa, MAP2, TUBIII, S100 were consistently high in both UA and tumor core samples and." (PMID 27605047, 2016). "Interestingly, the findings from both tumor models were remarkably similar and revealed one CAF-subtype that is characterized by co-expression of α-SMA, PDGFRβ, and NG2, while FSP-1 expression defines another CAF-subtype." (PMID 24734219, 2014). "Moreover, PDGFRα and PDGFRβ expression was detected by western blot in TGT44 tumors, confirming that these two pazopanib targets were also present in the tumor." (PMID 23937707, 2013). "Imatinib inhibits the activity of the dysregulated PDGFRB, decreases enzymatic activity in DFSP cells and inhibits their ability to divide and grow and induces apoptosis in tumor cells, which may have effects on decreasing tumor size." (PMID 23497641, 2013). "Imatinib, beside its original selectivity for Bcr-Abl tyrosine kinase, affects PDGFRβ, lowers IFP and microvessel density, and improves tumor oxygenation, consequently increasing the tumor concentration of small molecules such as docetaxel, or bigger ones such as liposomal doxorubicin." (PMID 24102047, 2013). "This combined therapy, significantly delayed the initial onset of tumor growth for both phenotypes, but resulted in the emergence of newer phenotypes as evident from the presence of unique/unfamiliar populations of MAP2+ and PDGFRβ+ cells." (PMID 22891161, 2012). "Additionally, several tumor related genes, including Maspin, WFDC1, SLPI, S100P, and PDGFRB, were shown to be differentially expressed in MGC803 cells in response to latexin expression." (PMID 21466706, 2011). "Cox regression for stromal PDGFRβ in tumor and non-malignant tissue of patients followed with watchful waiting." (PMID 20505768, 2010). "In multivariate Cox regression analysis including the known prognostic marker GS and local tumour stage, high stromal PDGFRβ in tumor and non-malignant tissue was not an independent prognostic marker (data not shown)." (PMID 20505768, 2010). "High PDGFRβ in non-malignant, fibromuscular stroma was correlated with large tumor size, advanced stage, epithelial cell proliferation and high Gleason score." (PMID 20505768, 2010).
tumor (continued). "These analyses confirmed that the majority of the PDGFRβ expression in the non-malignant fibromusclar and the fibroblast-like tumor stroma occurred in αSMA-positive cells." (PMID 20505768, 2010). "Moreover, in vivo corroboration remains lacking: the CM system merely simulates paracrine crosstalk, and we have not assessed PDGFRβ inhibitors in animal models to evaluate their effects on tumor growth, metastasis, or tumor microenvironment remodeling." (PMID 41601676, 2026). "Notably, DCN + cells were generally absent from the small PDGFRB+/SMA + vessels within the tumor cell nests." (PMID 40841830, 2025). "Specifically, in FOXL2+COL1A1− cells, we examined expression of other AGCT tumor markers such as SF1, calretinin, and inhibinα, whereas in FOXL2+COL1A1+ cells, we also examined expression of stromal markers, including αSMA, vimentin, S100A4, PDGFRa, PDGFRb, and FAP." (PMID 41042551, 2025). "In clinically established metastases, we showed that most tumor cells were clustered around small blood vessels (ERG+, SDF1+, POSTN+, SMA+, PDGFRB+), suggesting that other cell interactions, especially involving blood vessels, might drive later stages of metastasis growth." (PMID 40841830, 2025). "Therefore, it washypothesized that PDGFRβ could serve as a potential biomarker for HCC,which is a highly vascularized neoplasm, suggesting that this receptor could beoverexpressed in HCC compared to normal liver tissue." (PMID 41479565, 2025). "In our mouse models, PDGFRβ reliably discriminated EMT tumor cells from bonafide CAFs, but this may not be the same in other models." (PMID 36635273, 2023). "In summary, stroma-targeting PDGFRB and PARP inhibitors could significantly inhibit tumor growth." (PMID 37658364, 2023). "In contrast, the Oncotag treatment resulted in sustained downregulation of the pro-oncogenic molecules such as PDGFRβ, eNOS, PLC-γ1, JNK, p38α, Fgr, transcription factors STAT2, STAT5, and anti-apoptosis factor HSP27 and, probably, in long-term decrease in tumor aggressiveness." (PMID 37854069, 2023). "Importantly, tumor-blood-vessel analysis in the mouse model and human ASPS clarified that these vessels are well encapsulated with PDGFRB- and smooth muscle actin-positive pericytes, and that tumor-cell enclosure by pericytes is observed in the blood stream during distant metastasis." (PMID 37029109, 2023). "Some areas on the tumour cryosections showed a strong NIR signal without the presence of PDGFRB." (PMID 36139509, 2022). "Notably, both tumor center and invasion front harbored higher α-SMA+ stromal fibroblasts in WPOI 4–5 compared to the WPOI 1–3 tumors, which was confirmed by fibronectin and PDGFRβ immunoreactivity." (PMID 36045118, 2022). "Furthermore, analyses of PDGFRA and PDGFRB expression in pancancer tissues additionally demonstrated that the reduction of PDGFRA and PDGFRB at both mRNA and protein levels in tumor tissues might be a common event, as elucidated by previous studies." (PMID 36199822, 2022). "Furthermore, primary tumours with peritoneal involvement expressed higher levels of PDGFRB than those without peritoneal involvement." (PMID 36139509, 2022). "In addition to increased survival, Δ/Δ Pdgfrb mice had a decreased thymic tumor-to-body weight ratio, but spleen-to-body weight ratios were similar among the genotypes, consistent with an absence of splenic tumor development regardless of PDGFRβ status." (PMID 36045346, 2022). "Moreover, PDGFRβ stimulates VEGF-C and VEGF-A production using fibroblasts, which promote tumor lymphangiogenesis through the expansion of the lymphatic vasculature and CCA cell intravasation that contributes to the early spread to lymph nodes and, therefore, to metastasization." (PMID 36362726, 2022).